CRP (C-reactive protein)
Diseases named in the same sentence as CRP in open-access papers (continued):
Sharing a sentence is not in itself a finding about the gene and the disease.
pneumonia (continued). "In fact, the presence of serum hs-CRP values >61 mg/L in a patient with acute respiratory symptoms strongly suggests the diagnosis of pneumonia." (PMID 26772604, 2016). "Statistically, there was a significant difference in the CRP measurements among the major diagnoses—acute bronchitis, pneumonia and unspecified acute URTIs (X2=114.3, P<0.001, d.f.=4)." (PMID 26769226, 2016). "C-reactive protein (CRP) was first discovered in 1930 through a reaction with the somatic C polysaccharide of Streptococcus pneumonia in patients infected with pneumonia." (PMID 28190984, 2016). "All the children were entirely well between pneumonia episodes and showed an increase in inflammatory biomarkers (white blood cell count, neutrophils and C reactive protein) during the pneumonia." (PMID 26861259, 2016). "Based on our data, DNI showed higher accuracy than WBC and CRP for detection of superimposed pneumonia with ADHF in the ED." (PMID 27682424, 2016). "The AUC of initial DNI was significantly higher than the AUC of initial serum WBC and CRP in terms of predicting ADHF with pneumonia (p<0.001 and p = 0.047)." (PMID 27682424, 2016). "A small African study suggested that absolute total neutrophil count was more reliable than CRP or procalcitonin in differentiating neonates with pneumonia." (PMID 28702283, 2016). "Among the lower respiratory tract infections CRP was used most often among patients diagnosed with pneumonia (60.4%) and acute bronchitis (49.4%)." (PMID 27887585, 2016). "In animal models, human CRP protects against a lethal infection with S. pneumoniae, and in humans, it contributes to host defense during bacteremic pneumonia." (PMID 27100179, 2016). "The results of our study suggest that the routine use of serum CRP levels in hospitalized patients with acute respiratory symptoms can help clinicians to differentiate pneumonia from other respiratory infections." (PMID 27610265, 2016). "This reflects the inclusion of CRP tests in recent UK and Dutch guidelines on the management of suspected pneumonia." (PMID 27175799, 2016). "The multilevel likelihood ratio (LR) for intervals of CRP provided useful information on the posttest probability of having pneumonia." (PMID 27610265, 2016). "Meanwhile, our study also shows that these two procedures resulted in three shared AEs, i.e., chills (a feeling of coldness occurring during a high fever), pneumonia, and elevated CRP level in blood (indicating the occurrence of inflammation)." (PMID 27749923, 2016). "Increased serum CRP on admission has been demonstrated to be a relatively more sensitive marker in pneumonia patients than any clinical symptom or sign." (PMID 27682424, 2016). "In the receiver operating characteristic curves for initial DNI, WBC, and CRP for differentiating superimposed pneumonia in ADHF patients, the area under curve (AUC) of DNI (0.916 [95% confidence interval 0.859–0.955]) was good." (PMID 27682424, 2016). "An elevated WBC was observed in 38 episodes of pneumonia (86%).The most consistent inflammatory marker on the day of the diagnosis was an increase in CRP from baseline which was seen in 41 episodes of pneumonia (93%)." (PMID 26937636, 2016). "Median initial DNI, WBC, and CRP were significantly higher in the ADHF with pneumonia group [0% vs. 1.8%, p<0.001, 8,200 cells/mL vs. 10,470 cells/mL, p<0.001, and 0.56 mg/dL vs. 6.10 mg/dL, p<0.001]." (PMID 27682424, 2016). "In a multiple logistic regression analysis, CRP was the only positive predictor of CXR-confirmed pneumonia." (PMID 26821179, 2016). "Values of the ROC curves for DNI, WBC, and CRP for predicting superimposed pneumonia in patients with ADHF." (PMID 27682424, 2016). "Only three AEs (i.e., chills, pneumonia, and C-reactive protein increased) were shared by the BCG TB vaccine and bladder cancer vaccine." (PMID 27749923, 2016).
pneumonia (continued). "With these distinct AE profiles detected, this study also discovered three AEs (i.e., chills, pneumonia, and C-reactive protein increased) shared by the BCG TB vaccine and bladder cancer vaccine." (PMID 27749923, 2016). "Leucocytosis (WBC>11,000/ml) and raised CRP (>10 mg/l) were observed in 38 (86%) and 43 (97%) cases of pneumonia respectively." (PMID 26937636, 2016). "With respect to diagnoses, the distribution of CRP levels in the current study was higher in the clinically diagnosed pneumonia cases." (PMID 26769226, 2016). "The researchers examined the relations between the levels of CRP, leukocyte count, and erythrocyte sedimentation rate and the severity of pneumonia according to the criteria of different guidelines." (PMID 26567094, 2015). "For end-point pneumonia, CRP (cut-point >44.1 μg/mL) had the best overall discriminatory ability with 80.0% (95% CI 61.4–92.3) sensitivity and 78.7% (69.1–86.5) specificity." (PMID 26366571, 2015). "CRP had excellent discrimination between end-point pneumonia and normal CXR, while CHI3L1 and PCT were acceptable." (PMID 26366571, 2015). "The variables CRP, SpO2, presence of crepitations and wheezing are closely connected to the severity of pneumonia and we wanted to look at sub-populations based on these variables." (PMID 26407163, 2015). "The researchers showed that serum CRP levels taken at the time of a pneumonia diagnosis were better predictors of severity than NHAP prognostic scoring tools." (PMID 25821793, 2015). "The clinical decision model included clinical symptoms, vital signs, and C-reactive protein and provided high/low-risks for “pneumonia” and “other SBI”." (PMID 26024532, 2015). "Plasma levels of inflammation-associated proteins CRP and CHI3L1 were significantly higher in children with end-point pneumonia compared to the other groups." (PMID 26366571, 2015). "Several studies have indicated that CRP is feasible and accurate at differentiating pneumonia from acute bronchitis." (PMID 26672961, 2015). "Higher levels of CRP, PCT and CHI3L1 were associated with increased odds of end-point pneumonia compared to normal CXR." (PMID 26366571, 2015). "The monitoring of pneumonia with CRP has been validated as a follow-up during treatment of pneumonia with antibiotics." (PMID 26430738, 2015). "Larger studies should assess the promising performances of ProADM in pneumonia and other serious pediatric infections, as well as further comparisons with CRP and Procalcitonin." (PMID 26286191, 2015). "These included cigarette smoking, intravenous drug use, duration of HIV infection, reduced BMI or SAT, a prior history of pneumonia, and elevated peripheral leukocyte count or CRP levels." (PMID 25354261, 2014). "The best combination of clinical and molecular markers to predict severe pneumonia included respiratory rate, crackles, Lpc-2, and CRP." (PMID 24696240, 2014). "Clinically, the leukocyte (WBC) count and C-reactive protein (CRP) level are used to monitor pneumonia severity." (PMID 25371597, 2014). "Conversely, children presenting with pandemic S-OIV pneumonia were more likely to have a high level of CRP (19.7 ± 28.9 mg/L versus 8.0 ± 8.4 mg/L, P = 0.04)." (PMID 24696530, 2014). "The levels of IL-6, CRP and WBCs, and the mean body temperature were significantly higher in the pneumonia group than in the non-pneumonia group." (PMID 23935729, 2013). "Two patients died of pneumonia and respiratory failure later within the study period, and their initial hs-CRP levels were 18.78 and 18.81 mg/L, respectively." (PMID 24381758, 2013). "Pneumonia was defined according to World Health Organization guidelines, which were modified by including fever and white cell count, C-reactive protein, blood culture and chest x-ray." (PMID 24312321, 2013). "A blood sample for CRP was taken in 95.4% of all pneumonia episodes; the median value was 14.4 mg/L (IQR 8–200 mg/L)." (PMID 23320118, 2013).
pneumonia (continued). "Pneumonia was defined as a new infiltrate on chest radiograph in combination with clinical symptoms or elevated white blood count or plasma C-reactive protein." (PMID 24009703, 2013). "The current study shows that the risk factors for pneumonia are age, NIHSS, dysphagia, IL-6 and CRP." (PMID 23935729, 2013). "In the literature PCT is a superior diagnostic marker in pneumonia and other bacterial infections when compared to WBC and CRP." (PMID 23118979, 2012). "In summary, copeptin, PCT, WBC and CRP were good predictors of the development of any infection, pneumonia and UTI." (PMID 23118979, 2012). "In three patients pneumonia with infiltrates on chest x-ray, elevated C-reactive protein and elevated procalcitonine was diagnosed, and responded rapidly to antibiotic treatment, while immunosuppressive therapy regimen was not changed." (PMID 22629432, 2012). "This dichotomy of endpoints is reflected by our data: Whereas mortality was predicted by concomitant malignancy, chronic renal failure and high age, critical pneumonia was predicted by higher CRP levels indicating systemic inflammation." (PMID 22501026, 2012). "Batch 1 (WBC, CRP, copeptin) better predicted any infection (Wald-p<0.001) and pneumonia (Wald-p<0.001) than the best single predictor alone." (PMID 23118979, 2012). "The predictive value of vital signs, C-reactive protein (CRP) and X-ray findings for diagnosing pneumonia requiring antibiotics is low." (PMID 21521505, 2011). "In one of the datasets, we misclassified one single patient with pneumonia, because the corresponding C-reactive protein value was imputed with a value of <10 μg/ml." (PMID 21569472, 2011). "CRP levels were significantly higher in admitted patients (188 mg/L vs. 20 mg/L), further supporting our grouping of patients since CRP levels have been shown to predict severity of pneumonia." (PMID 20184731, 2010). "Despite disparity in results, procalcitonin (PCT) and C-reactive protein (CRP) are used for etiological diagnosis in children with pneumonia, assuming higher levels of both markers in bacterial infections when compared to viral ones." (PMID 20976241, 2010). "Nevertheless, especially in children with pneumonia, the analysis of CRP has been discussed to yield unsatisfactory results." (PMID 20302606, 2010). "We assessed the utility of PCT and CRP to differentiate viral from invasive bacterial pneumonia in children <5 years hospitalized with clinical severe pneumonia (CSP) in rural Mozambique, a malaria-endemic area with high HIV prevalence." (PMID 20976241, 2010). "Compared with the younger children, the older children had a more severe clinical course, manifested by longer total duration of fever, higher CRP, and a more severe pneumonia pattern." (PMID 20604923, 2010). "Such definitions included measurement of PCT and/or CRP on admission of children presenting with clinical pneumonia." (PMID 20976241, 2010). "This is mainly due to the fact that CRP can be increased in a number of inflammatory processes, for example, pneumonia, pancreatitis, pelvic inflammatory disease, and urinary tract infections." (PMID 20011658, 2009). "Some of the biomarkers which are at the offing as an adjunct in the diagnosis of pneumonia include C-reactive protein, leukocyte count, immunoglobulins, and proinflammatory cytokines." (PMID 20011658, 2009). "According to Smith and Lipworth, CRP can be used to differentiate between pneumonia and acute bronchitis." (PMID 20011658, 2009). "The authors showed that in patients with a good outcome the CRP concentration fell sharply, whereas in patients who died of pneumonia there was a progressive rise in the CRP level prior to death, to concentrations >10 mg/dl." (PMID 17723153, 2007). "Several studies have indicated that CRP is probably the most feasible and accurate investigation to differentiate pneumonia from acute bronchitis in patients with LRTI in general practice." (PMID 17394651, 2007).
pneumonia (continued). "CRP was also significantly higher in pneumococcal pneumonia than in aetiologically undefined pneumonia." (PMID 16433910, 2006). "The behaviour of CRP was similar to the expression of neutrophil CR1 in that CRP was significantly higher in pneumococcal and aetiologically undefined pneumonia than in influenza A pneumonia." (PMID 16433910, 2006). "Procalcitonin, C-reactive protein levels, leukocyte count, clinical variables and the pneumonia severity index (PSI) were measured." (PMID 16805922, 2006). "Our data show that the VAR is greater for CXR-confirmed pneumonia plus CRP ≥120 mg/l plus procalcitonin ≥5 ng/ml than that calculated using the very highly specific endpoints of serotype-specific or all-serotype pneumococcal bacteremic pneumonia." (PMID 15736995, 2005). "Among children infected with HIV with CXR-confirmed pneumonia, procalcitonin and CRP values were available for 139 (76.4%) of 182 vaccine recipients and 153 (73.2%) of 209 placebo recipients (p = 0.47)." (PMID 15736995, 2005). "The patient with pneumonia had a CRP value of 8 mg dl-1 before the operation and 9 mg dl-1 5 days after the operation, increasing to 50 mg dl-1 12 hours later." (PMID 16277717, 2005). "As observed in children not infected with HIV, the point efficacy estimate in children infected with HIV with CXR-confirmed pneumonia was greatest if both CRP and procalcitonin were at or above 120 mg/l and 5 ng/ml, respectively (52%; p = 0.004)." (PMID 15736995, 2005). "We thus evaluated the usefulness of procalcitonin and CRP to improve the specificity of CXR-confirmed pneumonia as an endpoint in vaccine efficacy trials." (PMID 15736995, 2005). "In particular, higher CRP levels later in the early postoperative course have been observed in patients who develop postoperative infections such as pneumonia, supporting CRP as a useful adjunct signal when evaluating respiratory decline in the postoperative period." (PMID 41598637, 2026). "Children with segmental/lobar Mycoplasma pneumonia were more likely to present with prolonged fever (>5 days), lymphocytopenia, a neutrophil-to-lymphocyte ratio (NLR) ≥ 3, and elevated C-reactive protein (CRP) levels, each of which was strongly associated with macrolide non-response (all p < 0.001)." (PMID 41892454, 2026). "The presence of high CRP levels in this case aligns with existing literature, supporting the hypothesis that inflammatory stress is a key driver of arrhythmogenesis in pneumonia patients." (PMID 40151738, 2025). "Patients diagnosed with pneumonia were, on average, significantly older (mean: 53.2 ± 2.4 months) than those with acute bronchitis (35.9 ± 2.0 months, p < 0.001) and had markedly elevated CRP levels (40.4 ± 3.1 mg/L vs. 14.2 ± 1.1 mg/L, p < 0.001)." (PMID 40941745, 2025). "Additionally, salivary CRP level was highly correlated with serum CRP levels in pediatric patients with pneumonia." (PMID 40871545, 2025). "We do not recommend CRP testing in children with acute cough.’10 Swedish guidance on community use of CRP testing similarly hinges on whether diagnosis is unclear, with potential for pneumonia, and also on the duration of symptoms." (PMID 40887118, 2025). "In the final multivariable model, the following variables were included: age, malignancy, liver cirrhosis, corticosteroid use, septic shock, elevated CRP, pneumonia, persistent bacteremia, and focus removal status (categorized as complete, incomplete, or absence of an eradicable focus)." (PMID 39776932, 2025). "C-reactive protein (CRP) POCT may help distinguish between pneumonia and self-limiting LRTIs with a similar clinical presentation." (PMID 40739482, 2025). "An additional limitation is the unavailability or high missingness of clinical variables in the first 6 h that may inform corticosteroid use in pneumonia including CRP as demonstrated in prior studies." (PMID 41287114, 2025).
pneumonia (continued). "Postoperatively, the patient's increased dyspnea, transition from dry to productive cough, desaturation, along with elevated CRP levels and radiographic findings of consolidations in bilateral basal zones and the right middle lobe, established the diagnosis of pneumonia." (PMID 40718209, 2025). "The results of the multivariate logistic regression analysis showed that age ≥ 60 years, comorbid COPD, PCT ≥ 2 ng/mL, CRP ≥ 100 mg/L, PaO2 < 60 mmHg, and PaCO2 ≥ 50 mmHg were independent risk factors for poor clinical efficacy of BAL in the treatment of severe pneumonia patients (all p < 0.05)." (PMID 41574374, 2025). "During the second episode (July 12, 2023–July 25, 2023), the rise in CRP could have been related to catheter reinsertion or suspected pneumonia." (PMID 40760640, 2025). "Interestingly, C-reactive protein (CRP) levels, ranged 35 mg/L to 146 mg/L, were significantly increased in children with HMPV-associated pneumonia than the normal level." (PMID 40346698, 2025). "In addition to identifying the frequency of pneumonia in these populations, this study aims to examine differences in patient demographics and key clinical biomarkers, including CRP, D-dimer, oxygen saturation, serum GRP78, and lymphocyte levels." (PMID 41226352, 2025). "Elevated CRP level is an important indicator for diagnosing pneumonia." (PMID 40529154, 2025). "In our study, ESR and CRP levels were elevated in cases requiring more intensive management, highlighting their role in severe pneumonia outcomes, particularly in the presence of complications like pleural effusion and empyema, though their impact was not independent." (PMID 41180631, 2025). "We hypothesized that a WBC count exceeding 15 × 109/L, combined with a CRP level above 70 mg/L, can assist in identifying KD patients with pneumonia-like changes." (PMID 39981208, 2025). "Children with severe pneumonia are at risk of developing ACD, which may be influenced by mechanical ventilation, CRP, PCT, IL-6, and IgA levels." (PMID 41234411, 2025). "In summary, children with severe pneumonia are at risk of developing ACD, which may be influenced by factors such as mechanical ventilation, CRP, PCT, IL-6, and IgA levels." (PMID 41234411, 2025). "The WBC and CRP data indicate heightened inflammation among patients with pneumonia." (PMID 40177646, 2025). "It is important to note that an elevated CRP level may be an indication of an undiagnosed preexisting infection, including subclinical pneumonia that was present at the time of surgery." (PMID 41375749, 2025). "A CRP test is only useful in patients without risk factors for severe outcomes where there is doubt about pneumonia." (PMID 40887118, 2025). "However, in the pneumonia subgroup, only T cells and their subsets were reduced, which was accompanied by elevated levels of the pro‐inflammatory factors CRP and IL‐6." (PMID 41146434, 2025). "Likewise, CRP and erythrocyte sedimentation values in individuals with pneumonia were also significantly higher than that in the control group (43.8 ± 51.2 vs 0.4 ± 1 mg/dL, p < 0.001 and 33.3 ± 22.7 vs 12 ± 2.8 mm/h, p = 0.033)." (PMID 38183438, 2024). "While CRP, PCT, NLR, PLR, and SII have shown associations with pneumonia in specific surgical populations, these general inflammatory biomarkers lack specificity for pneumonia pathogenesis." (PMID 39496632, 2024). "The NICE has recommended the use of CRP testing to predict pneumonia in primary care." (PMID 39609022, 2024). "Furthermore, no patients with severe pneumonia were found in the low CRP group, 2 (2.9%) patients with severe pneumonia in the middle CRP group, and 21 (29.17%) patients in the high CRP group." (PMID 38215120, 2024). "In one clinical trial, CAP caused by Streptococcus pneumoniae exhibited significantly higher levels of PCT and CRP compared to pneumonia not caused by Streptococcus pneumoniae, which aligns with our cohort data." (PMID 39844833, 2024).